ATR (ATR checkpoint kinase)
Diseases named in the same sentence as ATR in open-access papers (continued):
Sharing a sentence is not in itself a finding about the gene and the disease.
lung carcinoma (continued). "Our finding that MK1775-induced increase in CDK activity was accompanied by phosphorylation of CHK1 S317 in all lung cancer cell lines suggests that ATR might have a protective role after WEE1 inhibition similar to that seen in U2OS." (PMID 34359691, 2021). "However, combined inhibition of WEE1 and ATR appeared to reduce cell viability to a different extent in the four lung cancer cell lines, showing more than additive effects in H460, H1975, and SW900, but little synergy in A549." (PMID 34359691, 2021). "Similar results have been shown for AITC which induced replication stress-associated DNA damage in human lung cancer cells, where FANCD2 repair protein formed foci at stalled or collapsed replication forks, ATM/ATR, Rad18, and Chk1 were activated, and γH2A.X level was elevated." (PMID 31123866, 2020). "For example, it has been suggested that HR is the major pathway for the repair of DNA DSBs induced in response to protons in A549 lung cancer and glioblastoma cell lines, which would indicate that targeting ATR may be a successful radiosensitisation strategy." (PMID 32517381, 2020). "All of these results suggest that the presence of caffeine potentiates both HTB182 and CRL5985 lung cancer cells to cisplatin treatment by inhibiting ATR activity but inducing ATM activation, resulting in an increase in expression of the PUMA protein and an increase in apoptosis." (PMID 25937999, 2015). "Interestingly, another component of the Hippo pathway, LATS1, has very recently been involved in ATR-mediated response to replication stress in lung cancer cells." (PMID 26393999, 2015). "We undertook functional analyses of ATM, ATR, Chk1 and FA proteins in lung cancer cell lines." (PMID 26438152, 2015). "Here we sought to elucidate whether the ATM, FA and ATR pathways interact with each other and whether the ATM, FA and ATR pathways may be new diagnostic and therapeutic biomarkers for lung cancer." (PMID 26438152, 2015). "In this report, extensive in vitro and in vivo evidence is provided to support the hypothesis that ATR inhibition can improve lung cancer patient responses to DNA damaging agents." (PMID 25010037, 2014). "Among patients, frame shift insertion/deletion of ATR and the major mutation of RB1 (RB1 p.F739L) and TCF7L2 (TCF7L2 p.I271N) changed the protein structure during simulation, suggesting that they might play an important role in the development of lung cancer." (PMID 34970478, 2021). "Consequently, the combination of an ATR inhibitor with agents such as cisplatin could be an attractive therapeutic option for lung cancer and for other indications that have a reliance on ATR for survival following treatment with DNA damaging therapy." (PMID 25010037, 2014). "Radiosensitizing effects of DNA-PKcs (M3814), ATR (M6620), PARP (Olaparib), and IAP (Birinapant) inhibitors using a panel of lung cancer cell lines were studied." (PMID 41355183, 2025). "To clarify the effects of ATR inhibition specifically on DNA repair pathways, we tested the effects of AZD6738 on HR by investigating RAD51 formation in NCI-H460 and NCI-H1299 lung cancer cells." (PMID 39235982, 2024). "Human lung cancer and osteosarcoma cell lines (SW900, H1975, H460, U2OS) were treated with X-rays and ATR inhibitors (VE822; AZD6738) in the absence and presence of a pan-caspase inhibitor." (PMID 37346039, 2023). "Whereas, synergy effect in the combination of ATR inhibitor and WEE1 inhibitor is found in both high CCNE1-expressing osteosarcoma cell line and low CCNE1-expressing lung cancer cell lines." (PMID 37087441, 2023). "Effects of the WEE1 inhibitor MK1775 and ATR inhibitor VE822 were investigated in U2OS osteosarcoma cells and in four lung cancer cell lines, H460, A549, H1975, and SW900, with different sensitivities to the WEE1 inhibitor." (PMID 34359691, 2021).
lung carcinoma (continued). "In conclusion, we investigated the effects of WEE1 and ATR inhibitors, alone and in combination, on U2OS osteosarcoma cells and on a panel of four lung cancer cell lines with different sensitivities to the WEE1 inhibitor." (PMID 34359691, 2021). "POLQ, BRCA2, ATM, ATR, PARP4, and POLD1 alterations were most commonly observed in the entire advanced lung cancer cohort." (PMID 34604048, 2021). "To further evaluate this new exciting approach, we investigated the effects of combined ATR/WEE1 inhibition in U2OS osteosarcoma and four lung cancer cell lines." (PMID 34359691, 2021). "The protein expression levels of Cyclin E, cdc25A, ATM, p21, RRM2, γH2AX, and ATR/pATR were assessed via immunoblotting on samples from exponentially growing, untreated U2OS and lung cancer cells." (PMID 34359691, 2021). "This would contradict some very limited evidence suggesting a greater dependence on the HR pathway mediated by ATR for repairing DNA DSBs induced by protons, which was obtained using RAD51 siRNA in A549 lung cancer cells." (PMID 32517381, 2020). "BPDE treatment of lung cancer cells results in ATR/Chk1-mediated recruitment of Pol κ via Rad18 and the subsequent monoubiquitination of PCNA, and inhibition of ATR/Chk1 signaling prevents the interaction between Pol κ and PCNA." (PMID 30347795, 2018). "We next aimed to further characterize the biological effects of ATR- and CHK1 inhibition in our murine lung cancer cell line panel." (PMID 29138515, 2017). "Co treatment of lung cancer cell lines with IR and AZD7762 resulted in increased ATR/ATM mediated CHK1 phosphorylation, stabilised cdc25A and suppressed cyclin A expression, reducing survival in clonogenic assays." (PMID 28448462, 2017). "To rule out off-target effects of a particular ATR inhibitor, we confirmed the effects of ATR inhibition using a different ATR inhibitor in our lung cancer models for clonogenic cell survival and RAD51 foci formation." (PMID 39235982, 2024). "It has previously been shown that cancer cell lines including osteosarcoma, lung cancer and glioma stem cell lines that rely on the ALT pathway were hypersensitive to the inhibition of the protein kinase ataxia telangiectasia- and RAD3-related protein (ATR)." (PMID 37370681, 2023). "In lung cancer, the interaction of IQGAP3 with DNA repair protein Rad17 was essential for Rad17 expression and foci formation, the Mre11-Nbs1-Rad50 complex formation, and ATM/Chk2 and ATR/Chk1 pathways activation." (PMID 36275458, 2022). "We aimed to assess whether the ATR inhibitors VE822 and AZD6738, by abrogating the G2 checkpoint, increase cGAS-mediated type I IFN response after irradiation in human lung cancer and osteosarcoma cell lines." (PMID 36387237, 2022). "We therefore asked whether combined inhibition of ATR and WEE1 in the lung cancer cells would give a synergistic reduction in cell viability associated with induction of DNA damage in S-phase, such as was observed for U2OS cells." (PMID 34359691, 2021). "We concluded that combined treatment with WEE1 and ATR inhibitors gives a large synergistic reduction in cell viability in some, but not all, lung cancer cell lines." (PMID 34359691, 2021). "To explore the potential of combined ATR and WEE1 inhibition for lung cancer treatment, we used a panel of four lung cancer cell lines with previously identified large differences in sensitivity to the WEE1 inhibitor MK1775 (sensitive SW900 > H1975 > A549 > H460 resistant)." (PMID 34359691, 2021). "The clinically active ATR inhibitor, VE-822, also potentiated etoposide and the topoisomerase I poison, SN-38, in a panel of lung cancer cells, though not to the extent seen with gemcitabine and cisplatin." (PMID 28448462, 2017).
lung carcinoma (continued). "We sought to elaborate on these two observations by assessing the effects of the ATR inhibitor, VX-970, and the Chk1 inhibitor, AZD7762, on an extensive panel of lung cancer cell lines in combination with five DNA damaging drugs from various mechanistic classes." (PMID 25010037, 2014). "When lung cancer cells undergo DNA damage after radiation exposure and emit certain signals, RBM17 may sense these signals, translocate into the nucleus, facilitate the entry of MSI2, and subsequently interact with ATR, activating ATR along with CHK1 and other downstream molecules." (PMID 38645664, 2024). "The ATM/ATR inhibitor we used, also known as CGK-733, failed to inhibit ATM/ATR kinase activity in human lung cancer cells." (PMID 37021419, 2023). "No defects in ATM, ATR or Chk1 kinase activation, or FANCD2 monoubiquitination were identified in the lung cancer cell lines examined, including Calu6, and major alterations in these pathways were not identified in the TCGA database." (PMID 26438152, 2015). "When lung cancer cells are irradiated after knocking down MSI2, there is not enough MSI2 to enter the nucleus after DNA damage occurs, and it cannot interact with RBM17 and ATR to activate ATR, resulting in DNA damage repair not proceeding smoothly." (PMID 38645664, 2024). "When MSI2 is knocked down or inhibited in lung cancer cells, there is not enough MSI2 to enter the nucleus after DNA damage, so it cannot interact with RBM17 and ATR to activate ATR, which will not successfully complete DNA damage repair and increase tumor cell death." (PMID 38645664, 2024).
prostate carcinoma (56 papers, 2012 to 2026). A carcinoma that arises from epithelial cells of the prostate gland. "Consistent with these DNA damage response results, single sample gene set enrichment analysis (GSEA) of TCGA primary prostate cancers showed that those with RB1 loss had an increase in the gene set ATR Activation in Response to Replication Stress." (PMID 40436896, 2025). "As a monotherapy, ATR inhibitors have demonstrated synergistic efficacy in ATM-deficient prostate cancer models." (PMID 38672592, 2024). "In vitro models of prostate cancer with ATM loss were sensitive to ATR inhibition which was enhanced with the addition of PARPi." (PMID 37430137, 2023). "ATr blockers correlated with improved survival, while diuretics correlated with an increased risk of mortality from prostate cancer." (PMID 37746271, 2023). "Synthetic lethality is explored with PARP inhibitors in several cancers such as ATM-deficient tumors from breast and ovaries, aggressive prostate cancers in combination with ATR inhibitors, and high-risk neuroblastomas under ATR inhibition." (PMID 34359720, 2021). "The patient with advanced castration-resistant prostate cancer with neuroendocrine differentiation was a 53-year-old man with a tumour harbouring duplication of exons 1–3 in ATR, as well as BRCA2 and TMPRSS2-ERG somatic tumour mutations." (PMID 34040174, 2021). "Our data demonstrate that SPOP-mutated prostate cancer cells are hypersensitive to ATR inhibition in vitro and in vivo." (PMID 34599168, 2021). "Our finding that SPOP mutation triggers replication catastrophe, massive DNA breaks, and cell death upon ATR inhibition highlights that prostate cancers harboring SPOP mutations may be susceptible to treatment with ATR inhibitors." (PMID 34599168, 2021). "Herein, we purpose to underline the possible in vitro mechanism by which ATR could regulate prostate cancer cells and which indicates ATR II may provide a novel data for the application of ATR II in prostate cancer." (PMID 30545141, 2018). "The two molecules inhibited the activation of the endogenous ATR/Chk1 signaling pathway also in LNCaP prostate cancer cells." (PMID 41190242, 2025). "This study investigates the immunomodulatory potential of the ATR inhibitor (ATRi) tuvusertib to improve the targeting of prostate cancer (PCa) by immunotherapy." (PMID 41417226, 2025). "Mutations in the ATR gene were associated with high TMB in colorectal and prostate cancers; however, associations between individual DDR mutations and high PD-L1 expression were uncommon and tumour-type specific." (PMID 37821580, 2023). "Co-deletion of RB1 and RNASEH2B was associated with PARPi resistance in prostate cancer cell lines due in part to E2F1-induced BRCA2 expression, however, inhibition of ATR was able to overcome this resistance via disruption of E2F1-induced BRCA2 expression." (PMID 37430137, 2023). "Studies have shown that CDK8/19 inhibits premature G1/S conversion and ATR-dependent cell death in inducible prostate cancer cells." (PMID 35451651, 2022). "Germline ATR and ATM were associated with higher HRD in BRCA (FDR < 8.5 × 10−8), and germline ATM variants in prostate cancer (PRAD, FDR = 9.0 × 10−6), lung adenocarcinoma (LUAD, FDR = 5.8 × 10−5), and STAD (FDR = 0.007)." (PMID 34572800, 2021). "Here, we found that loss of NEIL3 activated radiotherapy resistance in the progression of prostate cancer potentially via the ATR/CHK1 pathway." (PMID 34591415, 2021). "We also examined the effect of ATR inhibition by VE-822 in a clinically-relevant setting by using the SPOP Q165P mutant patient-derived xenograft (PDX) model established from a prostate cancer metastatic lesion." (PMID 34599168, 2021).
prostate carcinoma (continued). "Androgen deprivation results in elevated activity of the TLK1B/NEK1/ATR/CHK1 pathway in prostate cancer cells and enzalutamide treatment reduces CDC6/ATR/CHK1 signaling." (PMID 33158305, 2020). "The combination of an ATR inhibitor and an AR-antagonist has recently shown improved efficacy in a prostate cancer xenograft model." (PMID 31242618, 2019). "The cytotoxicity of ATR II against human prostate cancer and normal cells was investigated by Cell Titer 96 wells cell proliferation assay." (PMID 30545141, 2018). "This notion was in line with a previous study that demonstrated KDM5D was involved in the regulation of ATR-dependent DNA damage repair of prostate cancer as shown by increasing CHK1 and cell division cycle 25C phosphatase (CDC25c) protein expression in response to KDM5D knockdown." (PMID 36982384, 2023). "In addition, it has been reported that the activation of CDK1/SPOP signaling by the ATR inhibition enhanced the cytotoxicity of ICIs in prostate cancer." (PMID 37528490, 2023). "We asked whether inhibiting ATR with the specific small molecule inhibitor AZD6738 (ATRi) could potentiate E2Fi-elicited cytotoxic effects in prostate cancer cells." (PMID 36230876, 2022). "Therefore, prostate cancer-associated SPOP mutation F133V impairs DNA re-replication checkpoint, promotes chromosomal instability, and leads to replication catastrophe when ATR is inhibited." (PMID 34599168, 2021). "ATM/ATR inactivation is a crucial step in promoting androgen-induced genomic instability and prostate carcinogenesis, and some missense variants of the ATM gene have been shown to confer a moderate increased risk of prostate cancer." (PMID 25540025, 2014). "The ATM/ATR DNA damage checkpoint functions in the maintenance of genetic stability and some missense variants of the ATM gene have been shown to confer a moderate increased risk of prostate cancer." (PMID 23272087, 2012). "Inhibition of CDC6 expression together with a Chk1/2 inhibitor, could reduce TopBP1 protein levels and ATR S428 and Cdc25C S216 phosphorylation, which results in inhibiting ATR-Chk1 signalling and synergistically increasing treatment efficacy in prostate cancer." (PMID 38685067, 2024). "With promising preclinical support, the efficacy of PARPi in prostate cancer is currently being investigated in combination with other agents such as anti-androgens, immunotherapeutics, chemotherapy, radiotherapy, and ATR (ataxia-telangiectasia and Rad3-related) protein inhibitors." (PMID 35804947, 2022). "In this study, we investigated the radiosensitising effects of three different DNA damage response inhibitors targeting ATM, ATR, and PARP in combination with X-rays and radium-223 on human prostate cancer cell lines." (PMID 38672592, 2024). "In line with the results presented here, previous studies have also demonstrated the synergistic activity of the ATR inhibitor BAY1895344 in combination with 223Ra across a range of in vitro and in vivo prostate cancer models." (PMID 38672592, 2024). "Consistent with previously published data, we determined that the ATR inhibitor, AZD6738, and the PARP inhibitor, AZD2281, radiosensitised all prostate cancer cells to low LET." (PMID 38672592, 2024). "As a next step, we performed a functional assay to establish the role of ATR/CHK1 and ATM/CHK2 pathways in the cell death induced by 6-TB and 7-TB in three human prostate cancer cell lines." (PMID 38783016, 2024). "ATR and CHEK1 expression levels are often elevated in many forms of cancer, including ovarian, breast and prostate cancer and correlate with poor outcomes for patients." (PMID 38669256, 2024).